IL15 (interleukin 15)
Diseases named in the same sentence as IL15 in open-access papers (continued):
Sharing a sentence is not in itself a finding about the gene and the disease.
lymphoma (50 papers, 2014 to 2025). A malignant (clonal) proliferation of B- lymphocytes or T- lymphocytes which involves the lymph nodes, bone marrow and/or extranodal sites. "This is in line with a previous study that linked IL-15 with lymphoma remission following CAR-T therapy." (PMID 40719826, 2025). "In a clinical trial of CD19 CAR T-cells for lymphoma, higher levels of IL-15 were associated with remission." (PMID 33643299, 2020). "A more prolonged administration of IL-15 might have induced greater therapeutic effects albeit balanced by an increased risk of lymphoproliferative disorder or lymphoma, either of which was seen in the IL-15 transgenic mouse." (PMID 32927646, 2020). "In addition, IL-15 is reported to associate with the effectiveness of immune therapy for patients with relapsed lymphoma." (PMID 29255466, 2017). "Similar to the CD19IL15 CAR-NK cells in lymphoma model, cytokine-armed NK cells (IL-21 and IL-15 NK cells) showed more significant tumor control than NT-NK cells." (PMID 40027823, 2025). "Previous CD19 CAR T cell studies in lymphoma demonstrated a significant association between CRS/ICANS and elevated levels of cytokines, including IFNγ, IL-2, IL-6, IL-8, IL-10, IL-15, and TNFα1,20–22." (PMID 39011120, 2024). "For example, delivering transgenes encoding CAR-CD19 and IL-15 using retroviral vectors into NK cells leads to the efficient killing of cancerous cells by CAR-NKs and production of the IL-15 in the murine model of lymphoma." (PMID 40007761, 2024). "To date, the most prominent success in NK cell adoptive transfer has been with IL-15-enhanced CAR-NK products against CD19-expressing lymphomas, while progress in other hematologic malignancies and solid tumor targets remain in earlier investigational stages." (PMID 36613644, 2022). "Combination therapy of IL-15 with rituximab in a mouse model of lymphoma and alemtuzumab in a model of adult T cell leukemia revealed that IL-15 enhanced efficacy of both rituximab and alemtuzumab." (PMID 35747794, 2022). "In an in vivo model, NKTR-255 showed a better PK and an increase of granzyme B and CD107a positive NK cells compared to IL-15 or IL-15 complexed with IL-15Rα, as well as better survival in mice bearing Daudi lymphoma xenografts." (PMID 35720368, 2022). "Most of the ongoing/recruiting early phase clinical trials of IL-15 based therapy in lymphoma patients are using IL-15 super agonists and in combination with other anticancer therapeutics due to the challenges with IL-15 monotherapy mentioned before." (PMID 35529882, 2022). "When IL-15 was integrated with CD19 CAR-NK cells against lymphoma, the cells expanded in vivo and remained detectable for at least a year after infusion." (PMID 34572387, 2021). "It was demonstrated that combination of IL-12/IL-18/IL-15-preactivated NK cells persisted at high cell numbers with potent effector function in lymphoma and melanoma tumor models in human and mice." (PMID 34768814, 2021). "Recently created IL-15 superagonist ALT-803 has shown promising results in clinical studies for lymphoma and NSCLC." (PMID 34768814, 2021). "Additional evidence supporting the importance of IL-15 for success of adoptive immunotherapy was acquired in a clinical study that tested the efficacy of CAR-19 T-cells in CD19+ relapsed lymphoma patients." (PMID 34372571, 2021). "In an example of this approach, CD19-CAR-specific T cells were modified to secrete IL15, and its anti-tumor efficacy evaluated using a xenogeneic model of lymphoma." (PMID 31024832, 2019). "In a clinical trial treating 22 patients with advanced stage lymphoma, patients with positive tumor responses and complete remissions had increased IL-15 serum levels." (PMID 30842774, 2019). "Afterwards, the same Tax-LUC model was utilized to investigate the role of IL-15 in spontaneous lymphoma development." (PMID 29643841, 2018). "A potential role of IL-15 in tumor immunosurveillance has also recently been reported in a mouse model of lymphoma." (PMID 25997501, 2015).
lymphoma (continued). "Taken together these findings establish that IL-15 represses tumor growth in Tax lymphoma by promoting tumor cell death." (PMID 24416335, 2014). "Interleukin-15 (IL-15) is known to enhance cytotoxic lymphocyte activity, and this study aimed to evaluate the efficacy and safety of a recombinant canine IL-15 (rcIL-15) as an adjunct to chemotherapy in dogs with lymphoma." (PMID 40520425, 2025). "Beyond lymphoma, IL-15-based therapies could have applications in other malignancies, where immune dysfunction plays a critical role." (PMID 40520425, 2025). "In conclusion, we demonstrated that IL-21 engineered, CD19-specific CAR-NK cells showed enhanced anti-tumor efficacy against CD19+ lymphoma cells both in vitro and in vivo settings, as well as increased persistence in a mouse xenograft model of lymphoma compared to IL-15 engineered CAR-NK cells." (PMID 40176196, 2025). "Thus, CD19.CAR NK cells co-expressing IL15/IL15Rα exhibited superior antitumor activity against lymphoma cells in vivo compared to CAR construct co-expressing soluble IL-15 or no cytokines." (PMID 37818365, 2023). "Additionally, IL-15-transduced cord blood-derived NK cells showed long-term antitumor activity and persistence in a mouse model of lymphoma." (PMID 36385211, 2023). "Similarly, another study investigated CAR-T/IL-15 cells in lymphoma and glioblastoma models, and they reported the downregulation of exhaustion markers and upregulation of antiapoptotic markers in CAR-T cells." (PMID 38201467, 2023). "The authors found that high serum IL-15 levels were associated with higher numbers of CAR-19 T-cells in the peripheral blood, and that IL-15 and IL-10 peak serum levels were significantly higher in lymphoma patients who achieved complete or partial remission." (PMID 34372571, 2021). "Interestingly, IL-15 SA administration provided GVT activity against A20 lymphoma cells in the murine donor leukocyte infusion (DLI) model without increasing graft versus host disease." (PMID 28574833, 2017). "Taken together, these findings identify IL-15 and IL-1α as therapeutic targets in lymphoma." (PMID 24416335, 2014). "This study was designed to determine whether IL-15 expression is a necessary prerequisite for lymphoma development in this mouse model, and whether systemic modulation of IL-15 activity is more likely to repress or stimulate similar malignancies in vivo." (PMID 24416335, 2014). "Some more obvious cytokines such as IL-2, IL-6, IL-7, and IL-15 have a direct link with T-cell lymphoma progression, and these cytokines’ expression levels have the potential to be used as biomarkers especially to predict the developmental stage of T-lymphoma tumor cells." (PMID 37746258, 2023). "Early clinical studies support their feasibility, as shown by FT596, an iPSC-derived CAR-NK engineered with IL-15 support, which demonstrated antitumor activity and a favorable safety profile in CD19+ lymphoma." (PMID 41487532, 2025). "An advanced allogeneic CD19‐CAR iNKT product co‐expressing IL‐15 and shRNAs against B2M/CD74 (to reduce HLA‐I/II expression) demonstrated efficacy in R/R non‐hodgkin lymphoma and acute lymphoblastic leukemia." (PMID 41292193, 2025). "IL-15 plays a crucial role in augmenting the proliferation, persistence, and homing of CD19 CAR cord blood-derived NK cells in a lymphoma-xenograft mouse model." (PMID 39633491, 2024). "Cord blood NK cells engineered to IL-15-expressiong CD19-CAR demonstrated potent anti-leukemic activity in vitro and improved survival in a murine lymphoma model." (PMID 39633491, 2024). "In lymphoma and leukemia research, a study noted improved performance in CAR-T cells targeting CD19 via the expression of the IL-15 gene and an inducible caspase-9-based suicide gene." (PMID 38201467, 2023). "IL-15 is a proinflammatory cytokine that contributes STAT activation by mediating JAK1 and JAK3 phosphorylation, leading to lymphoma cell growth and survival." (PMID 34079795, 2021).
lymphoma (continued). "UCB-derived NK cells transduced with a retroviral vector incorporating genes for CAR-CD19, IL-15 and inducible caspase-9-based suicide gene (iC9) killed CD19 positive cell lines and prolonged survival in a Raji xenograft lymphoma murine model." (PMID 34572387, 2021). "Other modifications have been incorporated in NK cells—in one such study, cord blood NK cells engineered to express IL15 and a CD19 CAR showed marked increase in survival in a xenograft lymphoma model." (PMID 31024832, 2019). "IL15-/-Tax-LUC mice were generated and resulted in an aggressive lymphoma development and accelerated mortality, suggesting that IL-15 contributes to the antitumor immunity in ATL." (PMID 29643841, 2018). "Multiple lines of evidence support a role for TAM in the biology of GC-derived lymphoma, in particular through their capacity to produce BAFF and IL-15." (PMID 26158216, 2015). "Recently, newly designed IL-21-armored CAR-NK cells were found to show significantly greater IFN-γ and TNF-α production and greater degranulation than IL-15-armored counterparts; this resulted in greater activity of CD19-CAR-NK cells against CD19-positive lymphoma in vitro." (PMID 39430751, 2024). "engineered CAR (iC9/CAR19/IL-15 T) T cells with a greater expansion potential (10-fold greater in vitro and 3- to 15-fold greater in vivo), greater persistence, and stronger antitumor effects in a SCID lymphoma human xenograft model." (PMID 39430751, 2024). "The IL-15-enhanced CAR T cells were able to expand 10-fold in vitro and 3- to 15-fold in vivo, and in the SCID lymphoma human xenograft model, the iC9/CAR.19/IL-15 T cells demonstrated greater effectiveness, along with better persistence and anti-tumor effects." (PMID 37251333, 2023). "To ascertain the function of IL-15 in Tax lymphoma, we created IL15−/− TAX-LUC mice and observed that IL-15 is not required for tumor onset or growth." (PMID 24416335, 2014). "The absence of IL-15 resulted in aggressive tumor growth and accelerated mortality and demonstrated that IL-15 was not required for Tax-mediated lymphoma but was essential for anti-tumor immunity." (PMID 24416335, 2014). "However, continuous IL-15 secretion was not reported to be problematic in lymphoma patients treated with anti-CD19 CAR-NK cells that were engineered to constitutively express hIL-15." (PMID 34372571, 2021). "In lymphoma models, CD19 UCB-derived CAR NK cells engineered to secrete IL-15 and lacking CISH have shown improved metabolic fitness and antitumor activity." (PMID 40510336, 2025). "iPSC-derived iDuo NK cells were engineered with three components of CD19-CAR, non-cleavable CD16 (hnCD16) and a membrane-bound IL-15/IL-15R (IL-15RF) fusion protein to effectively eliminate both CD19 and CD20 lymphoma under anti-CD20 mAb and to extend their in vivo persistence." (PMID 39633491, 2024). "Therefore, we analyzed the cytotoxic activity of OVA peptide-stimulated splenocytes obtained from the mice immunized with IL-15:IL-15Rα-B16F10-OVA, control-B16F10-OVA cells, or the “no virus group” against two OVA-expressing cancer cell lines, B16F10-OVA or E.G7-OVA lymphoma cells." (PMID 34439192, 2021).
influenza (49 papers, 2009 to 2025). An acute viral infection of the respiratory tract, occurring in isolated cases, in epidemics, or in pandemics; it is caused by serologically different strains of viruses (influenzaviruses) designated A, B, and C, has a 3-day incubation period, and usually lasts for 3 to 10 days. "The increase in IL-15 secretion is linked to lung injury in influenza by promoting the influx of CD8+ T cells." (PMID 34177897, 2021). "Expression of cytokines was reduced at 8 hpi, except for IL-15, which interestingly is implicated in influenza-induced acute lung injury." (PMID 31461941, 2019). "We show here that an IL-15 deficiency results in a site-specific reduction in NK cells from the lung airway and an exacerbation of viral load at early time points post influenza infection." (PMID 22624047, 2012). "In mice, lung-derived CCR9+CD4+ T cells migrate to the small intestine via the CCL25/CCR9 axis during influenza infection, contributing to dysbiosis and IL-15-driven Th17 polarization that exacerbates IL-17A-mediated intestinal injury." (PMID 40872830, 2025). "Although there was one study published that showed a conflicting report that IL-15 was involved in worsening influenzae pneumonia, the subsequent influenza vaccine has been successfully utilized in the murine model." (PMID 41008539, 2025). "Adequate plasma levels of ApoH are protective against severe influenza and RF and High levels of IL15 protect against RF." (PMID 39176097, 2024). "Actually, influenza and other respiratory viruses induce peripheral and local expression of IL-15, which is critical for anti-viral responses by different lymphocyte populations." (PMID 36238287, 2022). "IL-15 and IL-15 agonist complexes have also been evaluated for their ability to enhance vaccine-elicited immunity in many diseases, such as tetanus and influenza." (PMID 34578331, 2021). "Low concentrations of IL-15 alone induce negligible NK cell activation, but IL-15 is highly synergistic with other cytokines and with recall Ags, such as influenza, for NK cell CD25 and IFN-γ expression." (PMID 29491009, 2018). "Critically, IL-15 boosted the production of IL-12 in influenza-stimulated blood myeloid dendritic cells." (PMID 29491009, 2018). "Enhancement of NK cell IFN-γ and CD25 responses to influenza by low concentrations of IL-15 was evident to a similar extent in all NK cell subsets." (PMID 29491009, 2018). "It is known that DCs can potentiate NK cell functionality via enhanced IL-12 and IL-15 production after influenza infection." (PMID 29623077, 2018). "Further work will need to be done to determine if the addition of IL-15 to CpG adjuvanted influenza vaccines would boost protective anti-HA IgG productionin vivo in older individuals." (PMID 29479423, 2017). "Previous studies in TB, HIV, and influenza animal models have shown that MVA-based vaccines expressing pathogen-specific antigens as well as IL-15 elicited strong and durable protective immune responses." (PMID 26505634, 2015). "IL-15 in complex with IL-15Rα can help in recruitment and activation of NK cells during rhinovirus infection and IL-15 when blocked with an antibody appears to prevent NK cell recruitment into the BAL during influenza infection in mice." (PMID 25197644, 2014). "The same cytokines were shown to be elevated in infected individuals during the influenza pandemic in 2009 where expression of IL-12p70, IL-6 and IL-15 correlated with severe clinical outcome, although co-infection with SP was not confirmed in that study." (PMID 23421931, 2013). "Bacterial infection with Salmonella or Mycobacterium, or viral infection with Influenza has been shown to induce the expression of IL-15." (PMID 23028916, 2012). "Since IL-15 is known to be produced in the lung airways following influenza infection, we investigated the role of IL-15 in NK cell responses to influenza." (PMID 22624047, 2012).
influenza (continued). "Because we have previously reported that IL-15 is important for the migration of influenza-specific CD8 T cells into the lung airways, it was possible that those observed effects were secondary to the recruitment of NK cells to the lung." (PMID 22624047, 2012). "In contrast, NK1.1+CD3+ (NKT cells) were markedly reduced in the lung airways of IL-15-blocked mice, but overall, these cells represented a low proportion of the innate cells responding to influenza infection at these early time points following infection." (PMID 22624047, 2012). "By the same principle, viral control by NK cells can be therapeutically enhanced via intranasal administration of exogenous IL-15 in the early days post influenza infection." (PMID 22624047, 2012). "We and others have shown that following influenza infection, IL-15 message and protein is increased in the lung airways." (PMID 22624047, 2012). "Future work will attempt to tease out the roles of direct and indirect migration of both NK cells and CD8 T cells to IL-15 following influenza infection." (PMID 22624047, 2012). "Here, we have demonstrated that NK cells, which accumulate in the lung airways early after influenza infection, are dependent on IL-15 for this accumulation and subsequent ability to control viral load." (PMID 22624047, 2012). "Here, in a murine model of influenza, we show that virally-induced IL-15 facilitates the trafficking of NK cells into the lung airways." (PMID 22624047, 2012). "The addition of IL-15 adjuvants to vaccine regimens has previously been shown to enhance protective immunity against a variety of pathogens, including influenza, Toxoplasma gondii, and Herpes simplex virus (HSV)." (PMID 21408124, 2011). "It is possible that IL-15 present in the lungs of influenza infected mice (as detected from our whole lung mRNA array data) shuts down part of the APC function of IKDCs for CD4 T cells, as recently demonstrated in vitro." (PMID 19784375, 2009). "Furthermore, multiple studies have reported increased IFN-γ following influenza vaccination, while IL-15 as an adjuvant boosts CD4 T-cell immunity." (PMID 40881708, 2025). "Moreover, the dual role of T cells in influenza infection, mediating viral clearance while risking immunopathology, is further demonstrated by studies examining the effects of IL-15 signaling and CD8+ T cell activity." (PMID 40872830, 2025). "In a human challenge model of influenza, IL-6, IL-15, and MCP-1, among others, were highly upregulated in the first several days post-challenge in subjects who later developed symptoms; while serum samples from subjects with no symptoms post-challenge did not have elevations of these cytokines." (PMID 30557313, 2018). "Also, pulmonary dendritic cells were shown to maintain influenza-specific CD8 T cell responses via IL-15 signals." (PMID 29652930, 2018). "Moreover, we found that antibodies induced by H3 viruses, especially in the presence of IL-15, broadly bound to group 1 HAs, with moderate reactivity against group 2 and B influenza subtypes." (PMID 29479423, 2017). "In addition, IgG antibodies elicited by H3 viruses and/or IL-15 broadly bound to influenza HAs from both group 1 and group 2 influenza strains, which suggests potential use of CpG adjuvants and/or IL-15 agonists in influenza vaccination strategies." (PMID 29479423, 2017). "Although numbers of CD3+ NK1.1+ cells were also substantially reduced following anti IL-15 treatment, it is unclear whether this cell population plays a relevant role in controlling primary infections with influenza." (PMID 22624047, 2012). "We therefore first sought to determine whether NK cells responding to influenza infection were capable of receiving signals from this locally produced IL-15." (PMID 22624047, 2012).